SURF6 (surfeit 6)
Description:
Binds to both DNA and RNA in vitro, with a stronger binding capacity for RNA. May represent a nucleolar constitutive protein involved in ribosomal biosynthesis or assembly (By similarity).
Synonyms: FLJ30322; RRP14
Tractability: Small molecule: a structure with a bound ligand is known. PROTAC: ubiquitination databases record sites on it; its protein half-life has been measured.
Gene: Protein-coding gene on chromosome 9 (133,328,776 to 133,336,189, reverse strand). Ensembl gene ENSG00000148296.
Subcellular location: Nucleus, nucleoplasm; Nucleus, nucleolus
Subcellular location (Human Protein Atlas): Nucleoli; Nucleoli rim; Mitotic chromosome; Nucleoplasm
Gene Ontology:
Molecular function: molecular condensate scaffold activity; protein binding; RNA binding; DNA binding
Biological process: ribosomal large subunit biogenesis; ribosomal small subunit biogenesis
Cellular component: chromosome; nucleolus; granular component; nucleoplasm
Genetic constraint (gnomAD): Loss-of-function variants: 28 observed, 33.16 expected, observed/expected ratio (o/e) 0.84, 90% interval 0.62 to 1.16. The synonymous counts are far from expectation, so gnomAD's model fits this gene poorly and the ratio says little. Missense variants: 560 observed, 456.26 expected, observed/expected ratio (o/e) 1.23, 90% interval 1.14 to 1.32. Synonymous variants: 248 observed, 198.32 expected, observed/expected ratio (o/e) 1.25, 90% interval 1.13 to 1.39.
Homologues: Orthologues: chimpanzee SURF6 (99% identical), macaque SURF6 (89% identical), guinea pig SURF6 (76% identical), pig SURF6 (73% identical), mouse Surf6 (72% identical), dog SURF6 (72% identical), rat Surf6 (67% identical), tropical clawed frog surf6 (45% identical), zebrafish surf6 (42% identical), Caenorhabditis elegans gldi-11 (26% identical), Drosophila melanogaster Surf6 (19% identical).
Diseases named in the same sentence as SURF6 in open-access papers:
SURF6 is named in the same sentence as 6 diseases in open-access papers, as found by Europe PMC text mining. Sharing a sentence is not in itself a finding about the gene and the disease. The quoted sentences say what the papers report.
breast carcinoma (1 paper, 2023). "Increased DNA methylation in genomic regions associated with SURF6 and REXO1/CTB31O20.3 was linked to the length of time to diagnosis in the prospectively collected buffy coat DNA from individuals who subsequently developed breast cancer." (PMID 37309009, 2023).
chronic heart failure (1 paper, 2025). "GWASs have identified SURF6 in a causal association between chronic heart failure and the cerebral cortex and between gut microbiota and white matter injury and connectivity." (PMID 41488750, 2025).
cancer (2 papers, 2023 to 2024). A tumor composed of atypical neoplastic, often pleomorphic cells that invade other tissues. "Since SURF6 has not been studied in cancers, we investigated the correlation between SURF6 and CRC." (PMID 39523457, 2024).
infection (2 papers, 2023 to 2024). The state of being infected such as from the introduction of a foreign agent such as serum, vaccine, antigenic substance or organism. "Proteins downregulated during later stages of MVA infection showed a strong tendency to self-associate, including nuclear pore components, and a selection of nucleolar proteins associated with ribosome biogenesis (e.g. SURF6, RBM28, RPL7L1, ZC3HAV1, CDK105)." (PMID 38065956, 2023). "After ETBF infection, there is no significant change in the expression level of SURF6." (PMID 39523457, 2024). "Unlike miR3655, the expression of SURF6 did not change in CRC cells after ETBF infection." (PMID 39523457, 2024).
tumor (2 papers, 2023 to 2024). "Future research should investigate the potential applications of IRF7/IFNβ in KRAS mutant CRC, as well as the regulation of tumor-associated microbial ecology through the miR3655/SURF6 axis, providing insights into personalized treatment strategies." (PMID 39523457, 2024). "Using the TCGA database, we found that compared to normal tissues, the expression level of SURF6 is significantly elevated in CRC tumor tissues." (PMID 39523457, 2024). "Astonishingly, further analysis of the subcutaneously xenograft tumor samples from the nude mice revealed that silencing SURF6 significantly reduced the intratumoral abundance of ETBF." (PMID 39523457, 2024). "Compared to 20 KRAS WT, the expression level of SURF6 is higher in the 20 KRAS mutant CRC tumor." (PMID 39523457, 2024). "To verify whether SURF6 can promote the colonization of ETBF in CRC in vivo, we randomly divided the nude mice one-week after tumor formation." (PMID 39523457, 2024).
SURF6 also shares sentences with these, for which no sentence is quoted: colorectal cancer (1 paper).